INS (insulin)
Diseases named in the same sentence as INS in open-access papers (continued):
Sharing a sentence is not in itself a finding about the gene and the disease.
Cognitive impairment (continued). "This article reviewed the possible relationship between brain insulin resistance and cognitive deficits." (PMID 34108878, 2021). "Recently, the existence of a “cerebral” IR is defined as the failure of brain cells to respond to insulin and responsible for the appearance and progression of many forms of dementia and mild cognitive impairment (MCI) in late middle-aged adults." (PMID 33613266, 2021). "We furthermore found that the use of insulin inversely correlated to memory and visual-spatial tests, highlighting that patients with insulin therapy are prone to neuronal damage and cognitive impairment." (PMID 32629878, 2020). "Despite this, and analogous to LPS-induced cognitive deficits, insulin induced significant acute working memory dysfunction in ME7 mice that was absent in NBH controls." (PMID 32513828, 2020). "This article aims to clarify the relation between insulin resistance and cognition impairment, focusing on AD, the most common form of cognitive impairment." (PMID 32190448, 2020). "Recently, it has been revealed that insulin plays a vital role in the prevention of cognitive impairment derived from AD." (PMID 33171799, 2020). "Intranasal insulin administration has been shown to improve the cognitive function of healthy people and people with cognitive impairment, which validates the neurotrophic effect of insulin." (PMID 32112645, 2020). "Similar work on the proteomic signature of cognitive impairment in postmenopausal women with OSA also identified insulin as one of the biomarkers involved in the development of cognitive impairment." (PMID 31973065, 2020). "Accordingly, a more detailed in-depth analysis of central insulin resistance contribution to cognitive impairment is discussed later in this review." (PMID 32825356, 2020). "In accord with this observation, results suggest that Ori enhances insulin sensitivity to prevent the synaptic dysfunction and cognitive deficits in IR‐induced MHE." (PMID 31568638, 2020). "There are many clinical trials in AD patients who support these assertions and have shown that medication used to increase insulin levels has improved the condition of patients with cognitive impairments." (PMID 32503113, 2020). "Recent studies have shown that cognitive impairment and AD progression are related to a dysfunction in insulin signaling in the hippocampus and frontal cortex." (PMID 32825356, 2020). "Paeoniflorin can play a therapeutic role in STZ-induced cognitive deficits in mice by improving insulin signal transduction." (PMID 32774416, 2020). "Conversely, the chronic deficit of ADPN inactivates AMPK, reducing insulin sensitivity and inducing AD in elderly mice with the development of cognitive deficits and psychiatric symptoms." (PMID 32188008, 2020). "Other studies demonstrated that in early stage AD patients, an improvement or stabilization of their cognitive impairment was obtained with intranasal insulin administration, leading to increased brain insulin levels." (PMID 32708059, 2020). "We assessed locomotor activity and working memory, while manipulating glucose metabolism with LPS, 2-deoxyglucose (2-DG), and insulin to determine effects of altered glycemic status on sickness behavior and cognitive impairments in disease-naive and ME7 mice." (PMID 32513828, 2020). "We found that a condition reminiscent of insulin resistance occurs in the medial septum of 3 months old 3×Tg-AD mice, reported to develop typical AD histopathology and cognitive deficits in adulthood." (PMID 29736736, 2019). "Interference in the insulin signal processing in the brain has been indicated as the mechanism for the development of cognitive impairment in diabetic patients." (PMID 31661025, 2019). "This study explored the mechanism of berberine to alleviate cognitive impairment via the cholinergic anti-inflammatory and insulin signaling pathways." (PMID 31551793, 2019).
Cognitive impairment (continued). "We aimed to examine the effect of high-fat diet (HFD) on cognitive decline, and of cognitive impairment on food intake and body-weight, and explore efficacy of chronic intranasal insulin (INI) therapy." (PMID 31130848, 2019). "This is explained by the presence of numerous pathophysiological mechanisms that enhance cognitive impairment, which is related to impaired insulin function and vascular problems, all related to the beta-amyloid protein." (PMID 31662909, 2019). "It is a proof of concept that insulin desensitization is instrumental in driving cognitive impairments in AD, and that an improvement of insulin signaling has genuine benefits." (PMID 31068799, 2019). "Regardless, the end result is an eventual reduction in insulin secretion, therefore, lower brain insulin levels leading to further aggravation of synaptic and cognitive impairments." (PMID 30804755, 2019). "With this in mind, the present review will also summarize current knowledge on the efficacy of intranasal insulin to mitigate major pathological symptoms of AD, i.e., cognitive impairment and deregulation of Aβ and tau metabolism." (PMID 29743868, 2018). "Insulin treatment improved memory and cognitive function in patients with AD and in patients with mild cognitive impairment." (PMID 29385735, 2018). "Central nervous insulin delivery has long been proposed as a promising intervention to alleviate cognitive impairments for example in patients with AD." (PMID 30524368, 2018). "We explain how these incidents: (i) impair the insulin-signaling pathway and/or (ii) lead to cognitive impairment through hyperphosphorylation of τ protein, overexpression of amyloid-β and/or activation of microglia." (PMID 30563117, 2018). "While not significant, WT animals on a WD in our study, have the highest nominal insulin level, suggestive of a shift toward insulin resistance, a contributor to inflammation and cognitive impairment." (PMID 29444171, 2018). "In rodents, high-fructose diet decreases the phosphorylation level of insulin signaling pathway in hippocampus and cortex and contributes to cognitive impairment." (PMID 29258552, 2017). "The intranasal insulin delivery also has been proved to ameliorate memory in patients with mild cognitive impairment and AD." (PMID 29209211, 2017). "We found that intranasal insulin prevented both the short-term cognitive impairments and the long-term neurobehavioral abnormalities observed in 3xTg-AD mice." (PMID 28539885, 2017). "Intranasal delivery has been shown to be an effective way to deliver insulin into brain to alleviate memory deficit in patients with amnestic mild cognitive impairment or AD." (PMID 28356312, 2017). "Patients were less likely to persist with RAI when on ≤2 OADs versus ≥3 OADs and when having higher RAI out-of-pocket costs ($36 to <$56 versus $0 to $6.30) and more likely to persist when they had cognitive impairment and basal insulin use during follow-up." (PMID 27761472, 2016). "Strikingly, recent findings show that a clinical trial of intranasal insulin treatment improves cognitive function of patients with AD and those in the predrome stage, mild cognitive impairment (MCI)." (PMID 27058526, 2016). "Based on multivariable logistic regression analysis, the baseline factors found to be significantly associated with RAI persistence (Measure 1) at 12 months were cognitive impairment and addition of basal insulin during follow-up." (PMID 27761472, 2016). "Several small‐scale clinical trials have shown that intranasal insulin improves memory and attention in healthy participants, as well as in patients with mild cognitive impairment and AD." (PMID 27457264, 2016). "In patients with AD or mild cognitive impairment a single or repetitive administration of intranasal insulin improved memory and cognitive function." (PMID 27240327, 2016). "Glucose and/or insulin dysregulation can play a significant role in dementia-related cognitive impairments." (PMID 26823968, 2016).
Cognitive impairment (continued). "In the current study, we investigated the potential irreversible consequences of a HFD early in life on hippocampal insulin signaling and cognitive impairment." (PMID 27676071, 2016). "Pioneering participant-observation research, monitoring twenty-two “compassionate usage” Mild Cognitive Impairment and AD patients who have been on long-term intra-nasal insulin usage (2 years+) have shown marked improvement on intra-nasal insulin." (PMID 26933626, 2016). "In the present study using mice as an experimental model, we found that intranasal administration of insulin can prevent cognitive impairment, as well as biochemical changes in the brain, induced by general anesthesia." (PMID 26879001, 2016). "Our study provides novel evidence on the role of adiponectin in cerebral insulin sensitivity, development of AD-like pathologies and cognitive impairment." (PMID 27884163, 2016). "Another study supported the notion that the intranasal administration of insulin improves cognition in patients affected by mild cognitive impairment or AD." (PMID 26136647, 2015). "Intranasal administration of insulin was shown to be safe and effective in numerous studies in healthy humans and in patients with metabolic disease or cognitive impairment." (PMID 25705204, 2015). "Multiple lines of evidence have shown that ASK1 is involved in insulin signal, which plays an important role in AD pathology such as cognitive impairment." (PMID 24985705, 2015). "Several studies have explored the link between an insulin resistant brain state and cognitive impairment, particularly in dementia of the Alzheimer type as reviewed elsewhere." (PMID 26110057, 2015). "AD is also associated with increased oxidative stress, chronic inflammation, and cognitive deficits, as well as metabolic disturbances, such as impaired neuronal insulin signaling, impaired cerebral energy metabolism and reduced glucose metabolism." (PMID 26340637, 2015). "Low brain insulin levels and disrupted insulin signaling contribute to cognitive impairments directly, particularly in medial temporal lobe regions where insulin receptors are abundant." (PMID 25071557, 2014). "We recently found that brain tissue from patients with type-2 diabetes (T2D) and cognitive impairment contains deposits of amylin, an amyloidogenic hormone synthesized and co-secreted with insulin by pancreatic β-cells." (PMID 25149184, 2014). "For instance, short-term replacement of insulin in type I diabetic rats has shown to prevent cognitive deficits." (PMID 23776493, 2013). "In that case, insulin resistance and low insulin levels in the CNS (interestingly referred as ‘‘diabetes of the brain'') would lead to the accumulation of Aβ and cognitive impairment." (PMID 22701480, 2012). "Epidemiologic studies demonstrated that individuals with glucose intolerance, deficits in insulin secretion, or T2DM have a significantly increased risk for developing mild cognitive impairment (MCI) or AD-type dementia." (PMID 22329651, 2012). "In those on insulin, approximately one quarter had evidence of cognitive impairment and this significantly reduced their ability to understand the actions required in the event of a low blood sugar or acute infection." (PMID 21166853, 2011). "In the present study we identified a highly effective treatment of cognitive deficits of various origins with dicholine salt of succinic acid, the neuronal insulin sensitizer." (PMID 18215309, 2008). "Understanding these mechanisms could open new therapeutic avenues for targeting insulin pathways to mitigate both cognitive impairment and NPS in AD." (PMID 40819304, 2026). "Higher leg fat mass is associated with higher circulating adiponectin levels, so the “leg-dominant fat distribution” may prevent cognitive impairment by increasing adiponectin levels, reducing inflammatory markers, and improving insulin sensitivity." (PMID 41488045, 2025).
Cognitive impairment (continued). "Therefore, damage to the insulin signaling pathway compromises the structural and functional integrity of the central nervous system, leading to the development of cognitive impairments." (PMID 40909136, 2025). "Streptozotocin and high-fat diet-treated animal models are used to induce a combination of cognitive impairments, amyloid and Tau pathology, neuroinflammation, oxidative stress, impaired insulin signaling, and vascular changes, which are factors that have been implicated in the development of AD." (PMID 40720390, 2025). "Therefore, the study was designed to investigate the effects of dapagliflozin on cognitive deficits, insulin resistance, and mitochondrial dysfunction in the hippocampus of rats subjected to chronic restrained stress." (PMID 40397120, 2025). "The cognitive impairment that can ensue in the context of low brain insulin levels may be related to its ability to protect neurons from various insults including oxidative stress, ischemia, and glutamate-related excitotoxicity." (PMID 40253245, 2025). "In our study, in vivo experiments demonstrated that the supplementation of hesperetin with metformin elevated acetic acid, propionic acid, and butyric acid content, leading to improved cognitive impairment in DM rats through the protection of insulin signaling and the activation of CREB/BDNF." (PMID 40076550, 2025). "The potential role of disordered insulin homeostasis in cognitive impairment has been clarified." (PMID 40979705, 2025). "Enriching the refined diet with the fibers decelerated the aging-associated cognitive impairments while not affecting aging-related liver decline, insulin resistance or markers of intestinal barrier function." (PMID 40999272, 2025). "Hence, there was rationale for investigating intranasal insulin in PwMS who experience cognitive impairment." (PMID 40253245, 2025). "Taken together, these results suggest that disturbances in brain glucose metabolism and/or insulin signaling induced by APOE isoforms may be key to understanding the mechanisms of neurodegenerative changes in individuals with cognitive impairment." (PMID 39814004, 2025). "Pathological mechanisms linking IR to cognitive impairment include dysregulation of the insulin signaling pathway affecting hippocampal plasticity, amyloid precursor protein metabolism, tau protein deposition, neuroinflammation, and apolipoprotein E ε4 allele expression." (PMID 38622624, 2024). "Interventions to improve insulin sensitivity may serve as precautions against brain cortical atrophy and subsequent cognitive impairment." (PMID 39882263, 2024). "Although this study is a pilot study, which was conducted at a single institution on a homogeneous group of patients, our postoperative findings suggest a potentially positive role for intranasal insulin to prevent postoperative cognitive impairment and confirm that further study is warranted." (PMID 38915348, 2024). "The need for insulin injections and the technical skill required for insulin administration may pose challenges for patients, particularly those with cognitive impairment." (PMID 39335623, 2024). "In the context of T2D-related MCI, abnormal ribosome function could contribute to cognitive impairment through several mechanisms, such as impaired protein synthesis, endoplasmic reticulum (ER) stress, altered insulin signaling, and mitochondrial dysfunction." (PMID 39452046, 2024). "In conclusion, our study provides evidence that intracerebroventricular administration of insulin effectively attenuates LPS‐induced cognitive deficits, neuronal degeneration, and ferroptosis by enhancing glucose uptake and promoting the pentose phosphate pathway (PPP) in glucose metabolism." (PMID 39073013, 2024). "Furthermore, exercise reduces vascular risk factors, modulates glucose metabolism and resistance to insulin, which indirectly delays cognitive impairment." (PMID 39595479, 2024).
Cognitive impairment (continued). "Dysregulation of insulin signaling within the central nervous system modifies the functionality of both neuronal and glial cells at the synaptic interface and is correlated with neurodegenerative diseases and cognitive impairments." (PMID 39830570, 2024). "Those with physical or cognitive impairments may find it difficult to follow complicated insulin regimens that call for regular monitoring and adjustment." (PMID 39338179, 2024). "Our findings underscore this potential therapeutic property of fucoxanthin, considering the improvements in cognition and insulin sensitivity, which may preserve cognitive function in aging adults with mild cognitive impairment (MCI)." (PMID 39275314, 2024). "In our study, increased insulin levels were negatively correlated with cognitive impairment." (PMID 38542318, 2024). "Targeting the insulin signalling pathway may provide new strategies for the prevention and treatment of cognitive impairment." (PMID 39867560, 2024). "Increased insulin levels may support the development of neural circuits involved in cognition, while chronic mild inflammation may also result in cognitive impairment." (PMID 37887307, 2023). "Thus, the AT1R/Ang II axis links to pro-inflammatory and prooxidant effects, increasing BBB permeability, as well as cognitive impairment and tau hyperphosphorylation through the activation of GSK3ß, which has an essential role in the modulation of insulin." (PMID 36986785, 2023). "Consequently, damaged insulin signaling in the brain can significantly affect cognitive impairment and neurodegeneration." (PMID 37047044, 2023). "Despite these challenges, the favorable safety profile of intranasal insulin suggests that it may still be a viable therapy option for those with cognitive impairment." (PMID 37511207, 2023). "Insulin signaling of brain is particularly important for learning and memory, and that insulin resistance may lead to cognitive deficits in AD." (PMID 37095270, 2023). "Given the complex interplay between insulin and dementia pathogenesis, serum biomarkers related to insulin metabolism may exhibit abnormalities in cognitive impaired patients." (PMID 38105338, 2023). "Additionally, vildagliptin treatment effectively improved neuronal insulin sensitivity and prevented brain mitochondrial dysfunction, thus contributing to the alleviation of cognitive impairment induced by a high-fat diet." (PMID 38082288, 2023). "The effects of insulin on cognitive impairment are debatable." (PMID 36909158, 2023). "Interestingly, in human diabetic patients with mild cognitive deficits, Pio treatment improved peripheral insulin sensitivity, as well as plasma levels of Aβ and the insulin degrading enzyme." (PMID 37190025, 2023). "Investigating the neurobiological underpinnings of cognitive impairments in obese individuals, such as the impact of chronic inflammation, insulin resistance, and altered adipokine levels on brain structure and function, remains an essential subject for further exploration." (PMID 38137454, 2023). "In adults with mild cognitive impairment, daily treatment with long-acting intranasal insulin could also mitigate cognition dysfunction." (PMID 37575299, 2023). "Increasingly, literature has demonstrated that long-term HFD consumption results in insulin resistance, neuroinflammation, microglial activation, and oxidative stress in the brain, which contribute to cognitive impairment and psychiatric behavioral abnormalities." (PMID 36615907, 2023). "In the present study, KK-Ay mice displayed cognitive impairment, with glucose elevation, AGEs accumulation, oxidative stress, insulin resistance, reducing the contents of GLO1 protein, NADPH, or GSH, and MG (a major precursor of AGEs) hyperactivity in the brain or plasma." (PMID 37259448, 2023). "In addition, brain-insulin resistance reduces cerebral blood flow and cerebral cortex perfusion, which leads to cognitive deficits." (PMID 37373216, 2023).